LINC01213 (long independently transcribed non-coding RNA 1213)
Synonyms: LOC105374313
Gene: Long non-coding RNA gene on chromosome 3 (150,039,083 to 150,244,234, forward strand). Ensembl gene ENSG00000244541.
Diseases named in the same sentence as LINC01213 in open-access papers:
LINC01213 is named in the same sentence as 2 diseases in open-access papers, as found by Europe PMC text mining. Sharing a sentence is not in itself a finding about the gene and the disease. The quoted sentences say what the papers report.
prostate carcinoma (1 paper, 2022). A carcinoma that arises from epithelial cells of the prostate gland. "In order to evaluate the role of LINC01213 in prostate cancer, we first analysed the expression of LINC01213 in the TCGA database and found that it was upregulated in prostate cancer." (PMID 35310913, 2022). "We found that the expression of LINC01213 was overexpression in prostate cancer." (PMID 35310913, 2022).
cancer (1 paper, 2022). A tumor composed of atypical neoplastic, often pleomorphic cells that invade other tissues. "In addition, a previous study confirmed that LINC01213 plays an important role in cancers; Until now, the function of LINC01213 is in its infancy of prostate research." (PMID 35310913, 2022).